CEBPB (CCAAT enhancer binding protein beta)
Diseases named in the same sentence as CEBPB in open-access papers (continued):
Sharing a sentence is not in itself a finding about the gene and the disease.
tumor (continued). "One plausible explanation is that CEBPB’s impact on the DUSP1 promoter may depend on additional cofactors or epigenetic changes present in the tumor microenvironment." (PMID 41411347, 2025). "Apoptotic process was enriched, emphasizing enhanced tumor cell death following CEBPB knockdown." (PMID 41411347, 2025). "Finally, we demonstrated that CEBPβ up-regulated IGF2 expression in tumor senescent ECs by combining with Igf2-promtor-sequence." (PMID 39674501, 2025). "However, the cell type-specific regulatory role of CEBPB in tumor development and progression and immunosuppression in the TME remains to be fully elucidated." (PMID 40145099, 2025). "CEBPB: In tumor samples, CEBPB expression is high, as indicated by strong IHC staining (CAB004213)." (PMID 40104502, 2025). "Mechanistically, we revealed that SERPINA1 might mediate CEBPB-induced promotion of tumor cell growth and migration via STAT3 signaling for the first time." (PMID 38710698, 2024). "Besides, tumor glycolysis can regulate AMPK‐ULK1, autophagy, and CEBPB pathways to affect MDSCs and suppress anti‐tumor immune response in TNBC." (PMID 36373232, 2023). "First, we do not have a long follow-up of these enrolled CC patients to see whether patients with high level of FGFR2 and CEBPB were more prone to develop into tumor." (PMID 36996081, 2023). "In this study, we report that CEBPB, a transcriptional factor, is mainly expressed in macrophages in metastatic SKCM and associated with an active tumor immune environment and a favorable prognosis through integrated analysis of single-cell and bulk RNA-seq datasets." (PMID 36353635, 2022). "In conclusion, we present here the first report on CEBPB in tumor immune environment and prognosis regulation in metastatic SKCM and construct a reliable signature, which should provide a useful biomarker for stratification of the patient’s prognosis and therapeutic selection." (PMID 36353635, 2022). "For the important roles of macrophages in the determination of a relationship between the TME and tumor progression, we specially screened the macrophage-specific genes that were regulated by CEBPB in the metastatic SKCM and constructed a prognostic signature by using several CEBPB-regulated genes." (PMID 36353635, 2022). "However, ASS1 in T cells is still poorly expressed because of the tight chromosome that cannot bind to ATF4 and CEBPβ, resulting in impaired T-cell anti-tumor immunity." (PMID 36231064, 2022). "However, relationships between CEBPB and tumor immune landscape as well as the prognosis of metastatic SKCM have never been systemically reported." (PMID 36353635, 2022). "Past studies have implicated ATF5, CEBPB and CEBPD in the regulation of cancer cell responsiveness to the microtubule-targeting drug Taxol (paclitaxel), which is used to treat breast and other tumor types." (PMID 34065488, 2021). "CEBPB plays a vital role in cell proliferation and tumor development." (PMID 37303939, 2021). "We next investigated whether the expression of FOXO1/CEBPB/NF-κB/CCL20 signaling molecules had prognostic value using tumor tissues from CRC patients." (PMID 31395078, 2019). "In addition, when all CEBPβ isoforms were deleted in hematopoietic lineage cells using tumor mouse models, MDSC accumulation was diminished." (PMID 31404149, 2019). "The most significant, predicted activated upstream regulators in OS-2 (worse prognosis), relative to OS-1 tumor xenografts, were CEBPB and NFKB1 (P-value 5.54E–10 and 3.94E–09, respectively), whereas the most significant predicted inhibited upstream regulator was MEF2C (P-value 2.54E–23)." (PMID 27874835, 2016). "CEBPβ knockdown significantly decreased IL-1β-induced tumor cell invasion." (PMID 23342250, 2012). "Consistent with this, our data show that IL-1β-induced RCC tumor invasion was dependent on CEBPβ." (PMID 23342250, 2012).
tumor (continued). "In addition to the earlier noted suppression of tumor proliferation, its re-expression upon CEBPB knockdown may also contribute to reduced inflammatory responses mediated by MAPK." (PMID 41411347, 2025). "Notably, CellChat analysis unveiled diverse and extensive interactions between PCD-related cell clusters and tumor immune cells, highlighting the CEBPB+ CAF subtype as a signaling ligand communicated with other immune cell clusters through the Midkine (MDK)-Nucleolin (NCL) signaling axis." (PMID 40145099, 2025). "Interestingly, while C/EBPβ regulates whether menin’s activity in PDAC is tumor-suppressive or oncogenic, menin can, in turn, suppress the expression of C/EBPβ through recruitment of HDACs to the CEBPB promoter." (PMID 39336822, 2024). "Consequently, our research not only enhances our understanding of CEBPB's impact on tumor cells but also sheds light on its contribution to modifying the tumor microenvironment, thereby fostering the overall malignant progression of tumors during the carcinogenic process." (PMID 38994023, 2024). "In addition to canonical NF-κB pathways, STAT1, STAT3, JUN, EGFR, and CEBPB were also on the top list, and these proteins may play crucial roles in tumour-induced DC signal transduction." (PMID 28350008, 2017). "Dpep is a cell-penetrating peptide that targets transcription factors ATF5, CEBPB and CEBPD to selectively suppress growth and survival of diverse tumor cell types in vitro and in vivo." (PMID 42121927, 2026). "Decreasing in proliferation, invasion, migration, and EMT of MDA-MB-231 and A375 cancer cells in vitro and BC tumor size in vivo.↓ mRNA stability of PPARG, CEBPA, and CEBPB.↑ mRNA stability of SOCS1.↑ drug sensitivity." (PMID 41157107, 2025). "At the molecular level, transcription factors such as STAT1, CEBPB, HIF1A, and REL, collectively drive MDSCs expansion, while chemokines like CCL3, CCL4, CCL8 and IL1B regulate their migration within the tumor microenvironment." (PMID 41252877, 2025). "In summary, we identified a novel subset of CD34+CLDN5+ECs, with distinct senescent cellular features and high expression of IGF2, which was regulated by CEBPβ, primarily existed in the HCC tumor tissue." (PMID 39674501, 2025). "Continuing from our exploration of transcription factor networks in CRC, we conducted targeted experiments to knockdown CEBPB in HCT116, aiming to elucidate its pivotal role in gene regulation and pathway modulation within the tumor environment." (PMID 41411347, 2025). "CEBPB and Sp1 can potentially regulate CCL28, while only CEBPB was highly expressed in hypoxic tumor cells." (PMID 39075504, 2024). "For example, imatinib treatment of GISTs induces apoptosis in tumour cells, which further induces TAM M2-like polarization via CCAAT enhancer binding protein beta (CEBPB)." (PMID 39070147, 2024). "Presumably due to its capacity to interfere with the activity of CEBPB (and perhaps additional binding partners such as CEBPD), ST101 compromises the growth and survival of brain and other tumor cells in vitro and in vivo." (PMID 36831248, 2023). "We performed statistical analysis on the percentages of CEBPB+ve / FGFR2+ve bile duct cells / parenchymal cells between two groups, either CC vs. HB tumor group; or CC vs. HB non-tumor group." (PMID 36996081, 2023). "Dpep is a cell-penetrating peptide targeting transcription factors ATF5, CEBPB, and CEBPD, and that selectively promotes the apoptotic death of multiple tumor cell types in vitro and in vivo." (PMID 38001578, 2023). "It is clear from the literature reviewed above that a major response of brain and other tumor cells to ATF5, CEBPB and CEBPD knockdown or interference with activity is the appearance of apoptotic cell death." (PMID 36831248, 2023).
tumor (continued). "The most five active regulators were identical in tumor and normal tissues, SPI1, CEBPB, JUNB, FOS, and KLF4." (PMID 37335089, 2023). "We highlight one such strategy, namely, the design of cell-penetrating dominant-negative decoy peptides that exploit the leucine zipper properties of ATF5 and/or CEBPB and CEBPD, and that selectively suppress the growth and survival of tumor cells." (PMID 36831248, 2023). "A subsequent validation in a separate cohort of a larger series of CC and HB non-tumor livers revealed elevated expressions of FGFR2, CEBPB in CC patients, though other DE genes didn’t show differential expressions." (PMID 36996081, 2023). "As reviewed here, perturbation of ATF5/CEBPB/CEBPD affects a variety of properties of brain and other tumor cells such as their survival, growth, migration, mesenchymal transition, and response to therapeutics." (PMID 36831248, 2023). "Percentages of CEBPB-immuno-positive or FGFR2-immuno-positive bile duct cells in CC and HB-tumor liver were higher than that in HB non-tumor liver." (PMID 36996081, 2023). "Fto knockdown suppress the expression of transcription factors c-Jun, JunB, and CEBPB, restores the function of CD8+ T cells by impairing the glycolytic activity of tumor cells, thereby inhibiting tumor growth." (PMID 35672673, 2022). "A recent study reported that CP-DN-ATF5 can also interfere with endogenous CCAAT enhancer-binding protein beta (CEBPB) and delta (CEBPD) activities, whose inhibition promotes tumor cell death." (PMID 35806136, 2022). "A copious amount of literature links basic leucine zipper transcription factors, ATF5, CEBPB and CEBPD, to tumor formation, growth, metastasis and treatment resistance in a variety of cancers." (PMID 34065488, 2021). "IL6 and IL8 have been identified as direct CEBPB and CEBPD targets, and there is evidence that cancer-cell-derived IL-6 and IL-8 promote tumor growth and metastasis and therapeutic resistance." (PMID 34065488, 2021). "Previous tumor bulk analysis identified a related AP-1 family member FOSL2, together with CEBPB, STAT3, and TAZ, as important regulators of the MES GBM subtype." (PMID 34399888, 2021). "Tumor glycolysis coordinates the molecular network of AMPK-ULK1, autophagy and CEBPB pathways to affect MDSCs and maintain tumor immunosuppression." (PMID 33344447, 2020). "The accumulation of CEBPB is likely to modulate the NRF2 cistrome, which confers increased tumor-initiating activity on NRF2-activated NSCLCs by establishing the NRF2-NOTCH3 axis." (PMID 33219226, 2020). "The NOTCH3 enhancer generated by NRF2 in cooperation with CEBPB establishes the NRF2-NOTCH3 axis and drives malignancy of NRF2-activated NSCLCs by promoting tumor-initiating activity." (PMID 33219226, 2020). "The GSE54129 GC dataset and LASSO regression model (tumor vs. normal) were employed, and 6 significant differentially expressed genes (LAMP5, CEBPB, ARMC9, PAOX, VMP1, POC1A) were identified." (PMID 33052878, 2020). "The data showed that FOXO1, CEBPB, and FOXP3 expression in tumor tissues from CRC patients with chemoresistance was dramatically higher than that in chemosensitive tumor tissues." (PMID 31395078, 2019). "TF CEBPB can upregulate target gene PARD6B, whose expression is increased to promote MAPK signaling pathway for tumor cell proliferation." (PMID 31126066, 2019). "FOXO1, CEBPB, and RELA mRNA expression in stage IV tumor tissues was significantly higher than that in stage II tumor tissues, indicating that the signaling molecule signatures are closely correlated with the tumor stage." (PMID 31395078, 2019). "Lastly, CRC patients who received neoadjuvant chemotherapy with high levels of FOXO1, CEBPB, and CCL20 in tumor tissues showed worse overall survival." (PMID 31395078, 2019). "CEBPB shares functional interactions with CXCL10/IP-10, and both CEBPB and CEBPD are known to be tumor suppressors." (PMID 27764787, 2016).
tumor (continued). "For example, the chemokine CXCL10 promotes the infiltration of T cells into the tumor microenvironment, enhancing anti-tumor immunity, while CCL20 recruits Tregs via the FOXO1/CEBPB/NF-κB signaling pathway, thereby promoting chemotherapy resistance in colorectal cancer." (PMID 41200171, 2025). "By extension, re-establishing DUSP1 levels—either through CEBPB inhibition or direct DUSP1 upregulation—might represent a viable strategy to restore controlled MAPK signaling and reduce tumor aggressiveness." (PMID 41411347, 2025). "The major aim of this work was to determine whether Dpep, a cell-penetrating peptide that targets the leucine zipper transcription factors ATF5, CEBPB, and CEBPD, could effectively sensitize tumor cells to the cytotoxic actions of NK-92MI cells." (PMID 40358191, 2025). "Subsequently, we performed quantitative reverse-transcription polymerase chain reaction (qRT-PCR) to examine the expression levels of the seven key prognostic genes—CEBPB, TANK, MAT2B, TMEM165, CCDC167, CYFIP1, and COX17—in the CEBPB+CAF prognostic model in the tumor tissues." (PMID 40145099, 2025). "The co-expression and interaction of CEBPB and STAT3 may enhance oncogenic processes in ccRCC, contributing to its aggressive nature by shaping the tumor microenvironment through immune cell recruitment and activation." (PMID 40949418, 2025). "Our study illuminates the role of CEBPB in GBM subcluster 6, demonstrating its ability to recruit and polarize macrophages into the M2 phenotype by regulating the secretion of CCL2 and SPP1 by tumor cells." (PMID 38994023, 2024). "We also quantitated the percentages of parenchymal cells that were CEBPB+ve or FGFR2+ve in CC and HB tumor and non-tumor livers, and found that the percentages of CEBPB+ve and FGRF2+ve parenchymal cells were not significantly different between the three groups." (PMID 36996081, 2023). "In a test of the role of CEBPB (C/EBPβ) in PCa cell autophagy compliant with bortezomib treatment, the authors detected a reduction in the tumor growth rate of PC3 cells expressing shCEBPB, and reducing C/EBPβ enhanced sensitivity to bortezomib treatment in vivo experiments." (PMID 37569304, 2023). "Genes selected based on their log2FoldChange values for RT-qPCR verification in 31 CC and 11 HB non-tumor liver tissues revealed significantly elevated expression of FGFR2 in 7 and CEBPB in 2 CC liver tissues (CC vs HB: 4.082 vs. 0.7671, p<0.01; 2.506 vs. 1.210, p<0.01)." (PMID 36996081, 2023). "We found that CEBPB and FGFR2 were differentially elevated in the organoids and bile duct cells of CC patients and HB tumor region, and that elevated expression of FGFR2 and CEBPB may contribute to malignant transformation of CC." (PMID 36996081, 2023). "Above all, we speculated that CEBPB could prompt the polarization of macrophages to the immunologically stimulative subtype in metastatic SKCM TME and in turn inhibit tumor progression." (PMID 36353635, 2022). "We also examined the expression of CEBPB and AQP9 in the tumor tissues by immunohistochemistry." (PMID 35590355, 2022). "Our study indicated for the first time that knockdown of PGAM1 could reconstruct the expression of ASS1 in BC cells, resulting in a decrease in tumor growth and exerting antitumor effects via cAMP/AMPK/CEBPB axis." (PMID 35674458, 2022). "Strikingly, the protein complex formed by CHI3L1-Gal3 promotes the infiltration of “pro-tumour” M2 but not “anti-tumour” M1 macrophages and appears to be regulated transcriptionally by NF-κB/CEBPβ in the CHI3L1/Gal3/PI3K/Akt/mTOR axis." (PMID 36555253, 2022). "However, inhibition of the glycolytic process alleviates the tumour immunosuppressive state via AMPK-ULK1, autophagy pathway and CEBPB pathway." (PMID 36578477, 2022).
tumor (continued). "Downregulated genes include: 1) Immune system activators, such as CD86; 2) blood tumor suppressors ID2 and KLF4; 3) CEBPB, CEBPB is a BCR/ABL negative regulator gene, which can inhibit the proliferation of BCR/ABL-positive cells, and promote cell differentiation." (PMID 36699453, 2022). "Overall, our results pointed to the applicability of LOC102724169 as a tumor suppressor in OCCS, where CEBPB is a transcription factor during ontogeny, and which may result in the low expression of LOC102724169." (PMID 33850634, 2021). "The results indicated that CEBPB expression was significantly lower in stressed mice tumor tissues compared with non-stressed mice tumor tissues." (PMID 33850634, 2021). "ATF5, CEBPB and CEBPD are reported to promote tumor cell migration and metastasis." (PMID 34065488, 2021). "However, in line with TCR-TMART-1 responding to tumor PD-L1, CD8+ T cells in PD-L1low patients had higher expression of STAT3 and CEBPB, which are transcription factors for immune-suppressive cell subsets." (PMID 33754038, 2021). "Elevated accumulation of CEBPB in NRF2-activated NSCLCs is found to be one of the prerequisites for establishment of the unique NRF2-dependent enhancers, among which the NOTCH3 enhancer is shown to be critical for promotion of tumor-initiating activity." (PMID 33219226, 2020). "CEBPB accumulation in NRF2-activated NSCLCs is found to be one of the prerequisites for the establishment of the unique enhancers, in which NOTCH3 enhancer is critical for the promotion of tumor-initiating activity." (PMID 33219226, 2020). "By recruiting the methyltransferase DOT1L, CCAAT/enhancer-binding protein β (C/EBPβ, also known as CEBPB) could maintain an open chromatin state (H3K79 methylation) at multiple drug-resistance genes, thereby augmenting chemoresistance of tumor cells." (PMID 29712898, 2018). "In the current study, neither overexpression of nuclear C/EBPβ nor suppression of CEBPB expression showed evidence that supports tumor promoting or suppressive role of C/EBPβ." (PMID 25767874, 2015). "Importantly, CEBPβ activation has been correlated with increased invasiveness of RCC tumors in patients, suggesting it plays a role in the process of tumor cell invasion." (PMID 23342250, 2012). "This may suggest that the influence of CEBPB is relatively indirect, potentially affecting tumor progression through other mechanisms rather than directly determining the patient's survival time." (PMID 40949418, 2025). "Indeed, CEBPB and EP300, along with genes related to the Mitogen-Activated Protein Kinase (MAPK) signaling cascade such as MAP3K1, MAP2K2, and MAP3K11 were significantly upregulated in RMC tumor cells following treatment with nivolumab plus ipilimumab." (PMID 41290625, 2025). "In contrast, CEBPB is not detected in normal tissues, suggesting a tumor-specific upregulation." (PMID 40104502, 2025). "CEBPB may be more involved in the biological processes of the tumor rather than being a primary determinant of survival." (PMID 40949418, 2025). "Alternatively, CEBPB could modulate DUSP1 transcription in a context-dependent manner, activating expression in some conditions while simultaneously collaborating with other oncogenic signals to repress or override DUSP1’s tumor-suppressive functions." (PMID 41411347, 2025). "Indeed, CEBPB has proven to be nearly specifically expressed in the macrophages of metastatic SKCM tissues and regulates several immune response-related pathways in both macrophage and bulk tumor tissue in this study." (PMID 36353635, 2022). "In the current study, we used anti-CCL20 antibody to investigate tumor growth in vivo and found that blockade of CCL20 suppressed tumor progression and restored 5-FU sensitivity in CRC, suggesting that the FOXO1/CEBPB/NF-κB/CCL20 axis may be a potential therapeutic target for CRC." (PMID 31395078, 2019). "Distinctive positive staining in bile ducts were seen in CC, HB tumor and non-tumor liver tissues for FGFR2 and CEBPB." (PMID 36996081, 2023).